TPM1 (tropomyosin 1)
Diseases named in the same sentence as TPM1 in open-access papers (continued):
Sharing a sentence is not in itself a finding about the gene and the disease.
tumor (continued). "For example, miR-21-5p enhances tumor progression by targeting genes, such as leucine zipper transcription factor like 1 (LZTFL1), programmed cell death 4 (PDCD4), and tropomyosin 1 (TPM1)." (PMID 36768298, 2023). "miR-21 is able to negatively regulate phosphatase and tensin homologue deleted on chromosome ten (PTEN), tropomyosin 1 (TPM1), and apoptosis protein 4 (PDCD4), which in turn induces tumor cell growth, migration, invasion, and metastasis." (PMID 35216464, 2022). "The bioinformatics analysis of miR-21 predicted targets suggested that multiple tumor suppressor genes, including programmed cell death 4 (PDCD4), tropomyosin (TPM1), PTEN, and Fork-head box O1 (FoxO1) related to apoptosis pathways, have miR-21 binding sites." (PMID 36180486, 2022). "After intersecting genes in the yellow module of WGCNA with DEGs, we identified five myCAFs marker genes defined by previous single-cell sequencing that were significantly down-regulated in tumor tissues, including ACTA2, MYL9, TAGLN, TPM1, and TPM2." (PMID 35309916, 2022). "GEPIA database analysis indicated that those hub genes were significantly upregulated in the tumour tissues; however, VCL, TPM2, and TPM1 were significantly downregulated." (PMID 34112125, 2021). "hsa-miR-29b-3p was the most significantly expressed in the tumour tissues and regulated two hub genes, VEGFA and TPM1." (PMID 34112125, 2021). "miR-21 activates the EGFR/AKT signaling pathway via targeting tumor suppressor genes such as PTEN, PDCD4, APAF1, TPM1, TIMP3, RECK, FOXO1 and SPRY240." (PMID 32019988, 2020). "We identified six survival-related genes, EMP1, TPM1, NRP2, FGFR1, CAVIN1, and LATS2, found in the DEG analyses of both, tumor-paracancerous and paracancerous-normal differentially expressed data sets." (PMID 32695477, 2020). "In the same way, miR-10b was described as an oncomiR in BC by targeting tumor suppressive genes (e.g., PDCD4, PTEN, TPM1), thus promoting proliferation, invasion and metastasis, and predicting the worst BC prognosis." (PMID 32842653, 2020). "Mechanistically, it has been described that overexpression of miR-21 leads to the inhibition of several tumor suppressor genes, such as PTEN, TPM1 and PDCD4." (PMID 28915579, 2017). "Several potential miR-21 targets have been identified including some tumor suppressor genes such as phosphatase and tensin homolog (PTEN), tropomyosin 1 (TPM1) and programmed cell death 4 (PDCD4)." (PMID 26862856, 2016). "High (HMW) and low (LMW) molecular weight isoforms from TPM1 and TPM4 are altered in several cancer cells and the 3'UTR of TPM1 mRNA is tumour suppressive." (PMID 27649540, 2016). "Four genes, PPP1R3C, PHF21B, TPM1 and PPP1R14A, were highly downregulated in the tumor tissues compared with the normal tissues." (PMID 25789025, 2015). "Overexpression of tropomyosin 1 (TPM1) in MCF-7 cells suppresses anchorage-independent growth, whereas overexpression of miR-21 increases tumor growth." (PMID 26116372, 2015). "Another highly downregulated protein by IL27 was tropomyosin 1 (TPM1), which is known as a tumour suppressor." (PMID 26663990, 2015). "Three major targets of miR-21 include prominent tumor suppressors such as PTEN (phosphatase and tensin homolog), an important regulator of cardiovascular disease, PDCD4 (programmed cell death 4) and TPM1 (tropomyosin 1)." (PMID 29056711, 2015). "It targets the tumor suppressor genes PTEN, Tropomyosin alpha-1 chain (TPM1) and Programmed Cell Death 4 (PDCD4), thereby exhibiting oncogenic activity by promoting tumor cell proliferation and inhibition of apoptosis." (PMID 25886191, 2015).
tumor (continued). "Another widely expressed miRNA in hematopoietic and solid tumors is miRNA-21 miR-21 targets several tumor suppressor genes such as phosphatase and tensin homolog (PTEN), programmed cell death 4 (PDCD4), and tropomyosin 1 (TPM1)." (PMID 26056576, 2014). "MiR-21 functions as an oncogenic microRNA by targeting multiple tumor suppressor genes including PTEN, PDCD4, BCL-2, TPM1, and RECK, and its participation has been reported in many human cancers." (PMID 25428915, 2014). "As a result of the dysregulation, other proteins like MEIS1, MEIS2, TPM1, and ZEB1, which are putative tumor suppressors, are affected." (PMID 24391925, 2013). "miRNA microarray analysis has revealed that miR-21 was dramatically elevated in HCC tumor cells, with significant reductions of the expressions of several tumor suppressor genes, including PTEN, PDCD4, RECK and TPM1 (PTEN)." (PMID 24112539, 2013). "In the past 3 years, at least 3 direct targets of miR-21 have been identified, with all of them being tumor suppressors: the PTEN phosphatase, the actin-binding protein tropomyosin 1 and the reversion-inducing-cystein-rich protein with Kazal motifs." (PMID 23554630, 2010). "We detected significant previously undescribed underexpression in CRC for genes SLC26A3, TPM1 and DCN, with a suggested tumour suppressor role." (PMID 19678923, 2009). "When we looked for the function of these genes, we found that three (SLC26A3, TPM1, and DCN) of them play a tumour suppressor role." (PMID 19678923, 2009). "Significant negative correlation between the tumor grade and both TPM1 protein expression (r= -0.598, P < 0.001) and miR-183-5p (r=-0.502, P < 0.001) in tissue sections." (PMID 41231336, 2025). "The tumor stage showed a significant negative correlation with TPM1 protein ex-pression (r= -0.352, P < 0.05) and non-significant negative correlation with miR-183-5p (r=-0.244, p > 0.1) in tissue sections." (PMID 41231336, 2025). "Furthermore, Tropomyosin-1 (TPM1) has been found to upregulate E-cadherin expression while downregulating MMP-9 and VEGF expression, collectively inhibiting tumor metastasis in RCC." (PMID 41181710, 2025). "Further, muscle markers TPM1/ACTA1 and the recently described HNSCC differentiation marker KRT17 correlate in the cell cultures and the original tumor tissue, indicating that our differentiation model faithfully reflects the differentiation behavior in human tumors." (PMID 39030166, 2024). "But such results do not seem to affect the widely held belief that TPM1 plays a positive role in tumor tissues." (PMID 37686101, 2023). "TPM1 is involved in EMT, a key process in tumor invasion and distant spread." (PMID 37686101, 2023). "MiR-21 suppressed the action of various apoptotic and tumor suppressor genes including phosphatase and tensin homolog (PTEN), programmed cell death 4 (PDCD4), and tropomyosin 1 (TPM1) leading to an induction of cancer cell proliferation, and migration, as well as inhibiting apoptosis." (PMID 35684480, 2022). "Indeed, loss of LIFR down-regulated dormancy-related genes (e.g., thrombospondin-1 (TSP1), tropomyosin-1 (TPM1), TGF-ß2) and resulted in tumor cell dissemination to bone and osteolytic disease in vivo." (PMID 33809315, 2021). "On the other hand, TPM1, CASQ2, and CRYAB have low expression in BCa samples, which may indicate that they could serve as tumor suppressors." (PMID 31991631, 2020). "miR-21 has been reported as an oncomir that contributes to motility invasion and metastasis by targeting tumor suppressors such as phosphatase and tensin homolog (PTEN), tropomyosin 1, programmed cell death 4 (PDCD4) and mammary serine protease inhibitor (Maspin)." (PMID 25232827, 2014). "Differential expression analysis of the metastatic and primary tumor samples shows that a large number of the most highly downregulated genes such as TAGLN, ACTG2, TPM1, MYH111 and DES have been previously identified as expressed mostly in the prostatic stromal cells." (PMID 17430594, 2007).
tumor (continued). "In other words, a decrease in HMW TPM1/TPM2 might indicate a more aggressive tumor, but not necessarily bladder-specific." (PMID 40937226, 2025). "Furthermore, it was approved that treatment with anti-mir21 A15-SNA successfully inhibited oncogenic mir21 in mice, rescued the antioncogene TPM1, and suppressed tumor growth without noticeable toxicity while showing high stability in the tumor environment." (PMID 38951806, 2024). "Finally, an autocrine effect of tumor cell-derived EVs was also demonstrated by Dai and Gao, who found that miR-183 shuttled by PC3 derived EVs promotes cancer cell proliferation, migration and invasion through the inhibition of Tropomyosin 1 (TPM1)." (PMID 34616676, 2021). "Moreover, it has been reported that the over-expression of miR-21 is able to mediate cell survival and proliferation by targeting several potential tumor suppressor genes, like phosphatase and tensin homolog (PTEN), tropomyosin 1 (TPM1) and programmed cell death 4 (PDCD4)." (PMID 33374170, 2020). "However, non-tumor lung expression of miR-21, PTEN, MARCKs, TPM-1, PDCD4, and SPRY-2 did not significantly differ between LC-COPD and LC patients." (PMID 29371906, 2018). "Three proteins, caldesmon (CALD), heterogeneous nuclear ribonucleoprotein M (HNRNPM) and tropomyosin 1 (TPM1) were unique discriminative between LSCC and RSCC tumour cell-rich HND regions, however could not be identified as discriminative when the whole LSCC and RSCC tumour region were analysed." (PMID 40603632, 2024).
cancer (71 papers, 2009 to 2026). A tumor composed of atypical neoplastic, often pleomorphic cells that invade other tissues. "For example, a crude assay measuring total TPM1 protein would confound its many variants, yet different isoforms of the same gene can have opposing cancer associations." (PMID 40937226, 2025). "Tropomyosin 1 (TPM1) is a member of the tropomyosins (TPMs), which are actin-associated proteins that play a role in suppressing cancer progression." (PMID 33193757, 2020). "Overall survival and OSCC cancer-specific survival of the OSCC patients were associated with TPM1 expression." (PMID 28182650, 2017). "For instance, in the Vesiclepedia database, TPM1 is detected in urinary exosome datasets of several cancers, suggesting that it is present, albeit variably, in pathological states." (PMID 40937226, 2025). "Suppression of cancer cell-originated exosomal miR-183 has been suggested as an anti-cancer-modality for prostate cancer by affecting the expression of TPM1." (PMID 37250456, 2023). "Previous studies have identified the key role of TPM1–4 in some cancers, especially the role of TPM3 and TPM4 in HCC development." (PMID 34850589, 2022). "Upregulation of miR-21 is common to most types of cancer and is implicated in the suppression of genes associated with cell growth and differentiation such as PDC4, RECK, TPM1 and PTEN." (PMID 34871435, 2021). "The upregulation of TPM1 inhibited cell proliferation, induced apoptosis, and inhibited cancer growth in BC cells." (PMID 34112125, 2021). "Recent research demonstrated that TPM1 as an anti-oncogene has been reported in many types of cancer." (PMID 33499872, 2021). "In the present study, VEGFA, RRM2, H2AFX, CHEK1, CEP55, CDCA8 and AURKA were significantly upregulated; however, VCL, TPM2 and TPM1 were significantly downregulated in cancer samples of BC." (PMID 34112125, 2021). "Western blot analysis revealed that the expression of TPM1 was inversely related with the miR-21 expression in these 8 clinical samples, as the TPM1 expression was lower in the cancer tissue compared with the adjacent normal tissue." (PMID 33193757, 2020). "It was demonstrated by these results that patients who exhibited low TPM1 levels had worse cancer-specific and overall survival rates than those who exhibited high TPM1 levels in the cohort." (PMID 28182650, 2017). "The overall and cancer-specific survival of patients who exhibited low TPM1 levels were inferior to those of patients who had high TPM1 levels." (PMID 28182650, 2017). "Previous studies of HMW tropomyosins in breast and other cancers have focused exclusively on the gene products of the TPM1 and TPM2 genes." (PMID 28431393, 2017). "Although dysregulation of TPM1–4 expression may be related to the pathogenesis of some cancers, a comprehensive analysis of TPM1–4 in HCC is yet to be characterized." (PMID 34850589, 2022). "Upregulation of TPM1 may suppress the development of some cancers by inhibiting cellular morphologic transformation." (PMID 34850589, 2022). "Moreover, the migratory and invasion ability of cancer cells was enhanced by the destruction of stress fibres and by TPM1-mediated relevant adhesive structures." (PMID 34112125, 2021). "Furthermore, the potential involvement of TPM1 in the inhibition of cancer and vascular smooth muscle cell proliferation has been demonstrated." (PMID 34074003, 2021). "Therefore, elevated levels of inflammatory cytokines, which are associated with increased risk of both cardiovascular disease and cancer, appear to cause marked decreases in expression of HMW isoforms from TPM1 and TPM4." (PMID 27649540, 2016). "The increased expression of TPM1, TPM2 and TNC indicates a fundamental reprogramming of normal lung fibroblasts such that they exhibited a gene expression pattern that is typically found in carcinoma-associated fibroblasts." (PMID 25924783, 2015).
cancer (continued). "Of specific interest is the induction of TPM1, TPM2, TNC and POSTN, suggesting a fundamental reprogramming of lung fibroblasts such that the cells exhibit a gene expression profile that is typical for carcinoma-associated fibroblasts." (PMID 25924783, 2015). "As such, TPM1 may promote the sensitivity of docetaxel via regulating cancer cell stemness in CRPC." (PMID 37854295, 2023). "MiR-21 influences invasion and metastasis through its targets PTEN, TPM1, PDCD4, and the tumor suppressor maspin, making it a potential target for cancer therapy." (PMID 38726321, 2024). "MiR-21 modulates the expression of multiple cancer-related target genes such as PTEN, TPM1, and PDCD and significant over-expression of plasma miR-21 was observed even in patients with early-stage EC." (PMID 36199284, 2022). "In conclusion, the aberrant overexpression of miR-21 is common in cancer and promotes the migration and invasion of ESCC through inhibiting the TPM1 expression." (PMID 33193757, 2020). "All six selected survival-related genes (EMP1, TPM1, NRP2, FGFR1, CAVIN1, and LATS2) were reported to play a positive role in disseminating cancer cells or invasion in many kinds of cancers." (PMID 32695477, 2020). "Experimental evidence demonstrated that miR-21 is able to promote cancer through inhibition of several genes, such as phosphatase and tensin homologue (PTEN) on chromosome 10, tropomyosin-1 (TPM1), and programmed cell death-4 (PDCD4)." (PMID 29914173, 2018). "So far, validated targets of mir-21 included programmed cell death 4 gene (PDCD4), tropomyosin 1 (TPM1), phosphatase and tensin homolog (PTEN), chromosome condensation protein G (NCAPG), reticulon 4 isoform A (RTN4) and other cancer-related genes." (PMID 25098165, 2014). "Most of the candidate genes of which we confirmed cancer-specific AS in NSCLC are also involved in these processes (ADD3, CLSTN1, FN1, MYO18A, NUMB, SYNE2, and TPM1)." (PMID 21118496, 2010). "mir-21 was found to be over expressed in multiple cancers down regulated tumor suppressor genes (TPM1, PTEN, PDCD4 BASP1 and RTN4) in invasion and metastasis of cancer." (PMID 21114830, 2010). "In conclusion, we detected significant under-expression of genes SLC26A3, TPM1, DCN and CALM3 in CRC, providing further evidence of their decreased mRNA expression and thus implicating them in the development of this type of cancer." (PMID 19678923, 2009). "For instance, miR-21-5p could enhance the spread of HBC by targeting cancer suppressive genes, such as leucine zipper transcription factor like 1 (LZTFL1), programmed cell death 4 (PDCD4), and tropomyosin 1 (TPM1)." (PMID 34967265, 2022). "To further confirm that TPM1 is regulated by miR-21 in ESCC, we evaluated the TPM1 protein expression in 8 clinical ESCC samples (including cancer tissues and matched adjacent normal tissues) that had higher miR-21 expression in the cancer tissue compared with the adjacent normal tissue by RT-qPCR." (PMID 33193757, 2020). "MiR‐21 targets anti‐oncogenes and metastasis‐suppressing genes, like programmed cell death 4 (PDCD4), tumour‐suppressor gene tropomyosin 1 (TPM1), phosphatase and tensin homologue (PTEN) and Sprouty, thereby demonstrating its involvement in cancer growth, invasiveness and metastasis." (PMID 28799211, 2018). "In cancer cells, down-regulation of HMW-TPM1 expression could be the result of activation of the Ras/Raf/MEK/ERK pathway, or DNA methylation of TPM1 promoter, or over-expression of the onco-microR-21." (PMID 26263384, 2015). "Targets of miR-21 in cancer include PTEN, PDCD4, LRRFIP1, RECK, TIMP-3, TPM1, BTG2, and Sprty2." (PMID 25366985, 2014).
cancer (continued). "KEGG analysis revealed significant enrichment of DEGs, including TPM1, MYL1, and MYH3, in pathways such as cytoskeleton in muscle cells, alanine aspartate and glutamate metabolism, cGMP-PKG signaling pathway, central carbon metabolism in cancer, and Th17 cell differentiation." (PMID 41007361, 2025).
cardiovascular disease (7 papers, 2015 to 2023). "Recently, it has been demonstrated that TPM1 plays a key role in cardio-genesis and cardiovascular disorders, providing a link to the associations of SNPs from this gene with SBP observed in this study." (PMID 37895183, 2023). "Functional analysis of novel human mutations has provided proof that TPM1 is a candidate gene worthy of further screening for cardiovascular disorders." (PMID 28359939, 2017).
heart diseases (5 papers, 2015 to 2024). "The results allowed us to explain, at least partly, those molecular mechanisms by which the E98K mutation in the TPM1 gene impairs myocardial relaxation and leads to such a severe human cardiac disease as complex cardiomyopathy." (PMID 37569730, 2023). "Among them, hypertrophic cardiomyopathy (HCM) is the most common inherited heart disease, caused by mutations in more than 20 genes, including the TPM1 gene encoding cardiac tropomyosin (Tpm, Tpm1.1, or α-Tpm isoform)." (PMID 37569730, 2023). "Mutations in these structural genes, including TPM1, are linked to human heart diseases." (PMID 34302435, 2021). "Our work provides evidence that changes in Tpm1 AS may contribute to heart and muscle defects observed in RBFOX2 loss of function in human heart diseases and experimental animal models." (PMID 34302435, 2021).
)myopathies (4 papers, 2023 to 2025). "Interestingly, all of these genes are associated with genetic (cardio)myopathies in humans (TTN, NEB, MYBPC1, TNNT3 and TPM1) or mice (PDLIM3)." (PMID 37000196, 2023). "We hope that this review will stimulate interest for future work focused on the function of all TPMs, including TPM1 and TPM2 in skeletal muscle and in myopathies." (PMID 37936227, 2023).